IL6 (interleukin 6)
Diseases named in the same sentence as IL6 in open-access papers (continued):
Sharing a sentence is not in itself a finding about the gene and the disease.
infection (continued). "Additional analysis of several cytokines (Tnf-α, Il-6, IL-1β, and IFN-γ) and antimicrobial factors (Reg3γ, S100a8, and S100a9) found to increase during RIMD infection showed a similar trend, i.e., they were also strongly induced by infection with POR1 or POR2 but not POR3." (PMID 31848276, 2019). "DHEA treatment could not avoid the effect of cortisol on IL-6, IL-8, and MCP-1 expression but could partially avoid the inhibitory effect of cortisol on MMP-2 expression, as was demonstrated when infection experiments were performed in the presence of both cortisol and DHEA." (PMID 31695682, 2019). "Therefore, we quantified the production of cytokines produced by macrophages (IL-6, IL-10, TNFα, IFN-γ, GM-CSF and IL-1β□ in non-infected, Mtb-infection, HIV-infected and co-infected cultures over the course of an Mtb-infection using multiplex cytokine profiling." (PMID 31133636, 2019). "A multivariate model containing 5,6-dihydroxyeicosatrienoic acid, 8,9-dihydroxyeicosatrienoic acid, intercellular adhesion molecule-1, interleukin-6, and interleukin-8, could differentiate patients with VAP from brain injured patients without infection (AUROC 0.94 (0.80–1.00))." (PMID 30283005, 2018). "EV Y inoculation without infection did not stimulate the production of NO, but spleen cells from uninfected mice inoculated with EV Y and stimulated in vitro with TcAg produced lower levels of TNF-α, IFN-γ, IL-10, and IL-6 than did spleens cells from control mice." (PMID 29755471, 2018). "Past evidence suggests that there is wide variations in the correlation between ethnicity IL-6 and CRP levels, and given the non-white participants made up only 2% of the total sample, we felt its inclusion would not provide any meaningful comparison across categories of infection." (PMID 29198208, 2018). "Overall, these results suggest that IFITM3 may possess a mechanistically uncharacterized ability to dampen IL-6 production [43•] and also that IFITM3 may play underappreciated roles in preventing cytokine-driven immunopathologies, even in infections that are not directly restricted by IFITM3." (PMID 30662816, 2018). "We document a sharp increase in the inflammatory response in terms of Ifng, Tnfa, Il6, Il1b, Il1r1, Cxcl9 and Cxcl10 expression already on day 6 post-infection in WT mice, and of Cd8a on day 7, which were essentially absent in ST2-/- mice on day 5 to 7 after PbA-infection." (PMID 28448579, 2017). "The concentration of IFN-α as well as other cytokines (IFN-γ, G-CSF, MIP-1α, IL-6, and IP-10) is correlated with the severity of SFTS, suggesting that type I interferon may not be significant in resistance SFTSV infection in humans and it may play an import role in cytokine storm." (PMID 28086978, 2017). "Furthermore, IFN-γ, nitric oxide (NO), and IL-6 levels measured in colonic ex vivo biopsies increased until day six following CCUG 30485 strain (p<0.05–0.0005), but not C1 strain infection, whereas at day 16 p.i. respective mediators were comparable to those observed in colons of uninfected mice." (PMID 26406497, 2015). "In lung and spleen tissues of 3-week-old Pekin ducks taken at 24 h of infection with H5N1-tyTR05 virus, despite the detection of virus matrix gene expression, LITAF expression was significantly down-regulated (p < 0.05); IL-6 and IL-8 expression was not significantly affected (p > 0.05)." (PMID 25431115, 2014). "Interestingly, the cytokines whose levels were increased in HMA+ strains during mBMDM infection in vitro and in PECS ex vivo, including IL6, CCL5, and IL10, are not those that would be expected to change based on interference with known mitochondrial signaling pathways (i.e., MAVS, NF-kB, IRF3/7)." (PMID 24781109, 2014).
infection (continued). "Second, inflammatory mediators such as IL-1β, tumor necrosis factor α and IL-6, which could elevate serum PCT levels in some elderly patients, especially those with poor immune response and those with local infections in early stages, might not be induced as soon as bacterial colonization." (PMID 24393388, 2014). "Thus, even when murine infection is initiated with MHB-grown Ft the inflammatory response to actively replicating (now, host-adapted) bacteria at 24 h fails to include TNF, IL-1β, and IL-6." (PMID 23554897, 2013). "Our results not only confirm what other laboratories have reported with regard to extracellular exposure of astrocytes to gp120, but we have also shown that non-productive infection of astrocytes by HIV-1 may be a significant and persistent source of IL-6 in the CNS." (PMID 21712995, 2011). "Influenza A virus (H3N2) infection of undifferentiated human bronchial epithelial cells NCI-H292 leads to induction of RANTES, IL-6 and IL-8 secretions, but not granulocyte-macrophage colony stimulating factor; these may be relevant in host defense and pathogenesis." (PMID 20090947, 2010). "Given clinical evidence of systemic inflammation in the absence of infection, we hypothesized that the fever was likely a cytokine-mediated phenomenon similar to cytokine release syndrome (CRS) and examined plasma levels of pro-inflammatory cytokines IL-6, TNF-α, and IFN-γ." (PMID 37626859, 2023). "Additionally, IL-6 plays a role in epithelial repair following lung injury, hence the proteolytic degradation of this cytokine during non-mucoid PA/HRV infection might hamper the repair of pathogen-induced damage." (PMID 35265536, 2022). "However, there were no significant changes in serum IL-6, TNF-α, and IL-1β levels under the same condition; moreover, we did not observe any reductions in damage to the lungs and kidneys (organs that are vulnerable to severe infection) in CdCl3-pretreated mice after CLP." (PMID 33564275, 2021). "Interestingly, both COX-2 inhibitors downmodulated IL-6 secretion regardless of infection compared to uninfected and untreated cells (P = 0.029), however in the presence of T. gondii, COX-2 inhibitors did not change the levels of IL-6 in comparison to untreated and infected cells." (PMID 30809216, 2019). "As we identified no detectable infection driven expansion of vaccine-specific CD4+ T cell populations during the four day culture, we proceeded to investigate whether we could detect infection specific cytokine response (IFN-γ, IL-1β, IL-6, IL-10, IL-12p70 and TNF-α) in the culture supernatant." (PMID 28588268, 2017). "Additionally, it should be noted that even during the early onset of infection with negative DTH response (III profile) IL-6 showed significantly higher serum levels than those of TNF-α, IL-4, and IL-10, suggesting that it exerts a latent immunopathogenic effect even during early infection onset." (PMID 27051668, 2016).
cancer (7,104 papers, 1993 to 2026). A tumor composed of atypical neoplastic, often pleomorphic cells that invade other tissues. "On the other hand, it can alternatively activate macrophages into a pro-inflammatory phenotype, inducing cytokines such as IL-6, which are associated with cancer cell proliferation, drug resistance, and poor prognosis." (PMID 41601657, 2026). "The treatment also reduced the levels of molecules linked to inflammation and cancer progression, such as IL-6 and STAT3, and disrupted the internal skeleton that helps cells divide and spread." (PMID 41514893, 2025). "In cancer cachexia, IL-6 is known to cause muscle and fat loss by activating the JAK-STAT signaling pathway." (PMID 40469669, 2025). "TNF and IL6 inhibitors can increase the incidence of some malignant tumors and the risk of Mycobacterium tuberculosis reactivation." (PMID 40565149, 2025). "For example, the cytokine IL-6 was upregulated in various types of cancer and a deficiency of IL-6 rendered mice resistant to the development of murine plasmocytoma." (PMID 40305194, 2025). "CRP, a pentameric protein synthesized by the liver in response to IL-6 during inflammation, has been linked to vascular disease, respiratory issues, cancer, and increased mortality risk." (PMID 41403880, 2025). "IL-6 also drives other inflammatory factors (e.g., C-reactive protein) that are pertinent risk factors for diseases and conditions, including cancer and lower-back pain." (PMID 40740426, 2025). "Our model’s predictions further underline the major role of IL-6, which was found to be increased even in mild virtual patients in the cancer and immunosuppressed VPCs." (PMID 40489562, 2025). "IL-6 is a pro-inflammatory cytokine that plays a pronounced role in cancer metastasis and is clinically associated with poor prognosis in cancer patients." (PMID 41382246, 2025). "Previous research has shown that IL-6, a key cancer-associated inflammatory cytokine, enhances invasion and migration of GBM cells." (PMID 41446725, 2025). "Elevated IL-6 levels have been implicated in the development of hormone resistance in PCa, further emphasizing the interconnectedness of systemic inflammation, cancer progression, and microbiome health." (PMID 40909933, 2025). "In particular, an inverse correlation between MedDiet and chronic inflammation, with lower levels of inflammatory biomarkers (i.e., CRP and IL-6) and lower risk of several cancers, has been reported." (PMID 40732979, 2025). "ILs, including IL-6, IL-8, and IL-10, among others, are intimately associated with cancer progression." (PMID 41200178, 2025). "In the CRC microenvironment, IL-6 stimulates cancer-associated fibroblasts (CAFs), which in turn further secrete IL-6, creating a positive feedback loop that sustains chronic inflammation." (PMID 41007818, 2025). "Elevated IL-6 levels have been consistently associated with adverse outcomes across different cancer types 9-11." (PMID 39781345, 2025). "Then, considering the untreated pts cohort, a significant reduction in IFN-α, commonly associated with an anti-cancer response, and IL-6, a cytokine with a more enigmatic but protective role against cancer, was found over time during follow-up." (PMID 40251644, 2025). "Patients with higher serum IL-6 levels exhibited a greater susceptibility to BM, while data from the cancer genome atlas indicated that individuals with lower IL-6 levels had improved overall survival rates." (PMID 39858080, 2025). "A meta-analysis incorporating 80361 cases and 78712 controls from 97 case-control studies was carried out to evaluate the association between IL-6 promoter polymorphisms and cancer susceptibility." (PMID 39980561, 2025). "In acute immune responses, including those to infectious diseases and cancer, NF-κB is activated in alveolar macrophages, causing overproduction of IL6, whose elevated levels trigger a cytokine storm." (PMID 40650062, 2025).
cancer (continued). "IL-6 is a proinflammatory cytokine that plays a crucial role in cancer progression and high levels of IL-6 are associated with promoting tumorigenesis, invasiveness, and metastasis in various types of cancer." (PMID 39762212, 2025). "IL-6 is a key proinflammatory cytokine implicated in cancer cachexia, immune suppression, and resistance to therapy." (PMID 40650134, 2025). "Quercetin-loaded nanoparticles have demonstrated the ability to inhibit the NF-κB signaling pathway, leading to decreased secretion of IL-6 and IL-8—cytokines implicated in cancer cell survival and chemoresistance." (PMID 40356750, 2025). "Cancer associated fibroblasts coordinate immune suppression through three core mechanisms: cytokine network (TGF-β/IL-6), metabolic symbiosis (lactate/arginine consumption), and immune checkpoint crosstalk (PD-L1/CD73)." (PMID 40934009, 2025). "We found that in systemic circulation, pre-Cx cancer progression was associated with moderate increases in IL-6 and GDF15 concentrations, dramatic induction of positive-APP production and marked reductions in the levels of most amino acids." (PMID 40124481, 2025). "The IL-6/albumin ratio has emerged as a more specific marker, integrating inflammatory status with nutritional assessment to improve diagnostic accuracy in cancer-associated muscle wasting." (PMID 41220691, 2025). "IL-6 genotypes such as 174GG and 634GG correlate with increased cytokine production and have been associated with cardiovascular disease and cancer predisposition." (PMID 40650134, 2025). "In BC, elevated interleukin-6 (IL-6) levels contribute to an inflammatory signature linked to cancer stem cell (CSC) stemness and depressive behaviors." (PMID 39896297, 2025). "Our objective was to evaluate the strength of the association between circulating IL-6 levels, measured in cancer patients before and after initiating ICIs, and the risk of irAEs." (PMID 41019062, 2025). "Mechanistically, cancer-associated adipocytes (CAAs) secrete IL-6 and release free fatty acids (FFAs), which serve as metabolic sensors to activate ANGPTL4 via STAT3 and PPARα signaling pathways in TNBC cells." (PMID 40616161, 2025). "Key proinflammatory factors associated with cancer include interleukin (IL)-1β, IL-6, and tumor necrosis factor alpha (TNF-α), along with the transcription factors NF-κB and STAT3." (PMID 41502528, 2025). "In humans, acute bouts of exercise mainly high intensity, has elicited significant increases in systemic IL-15 and other myokines (e.g., IL-6, oncostatin-m) that have been implicated in the suppression of cancer growth in pre-clinical and in-vitro models." (PMID 41350482, 2025). "Specifically, the IL-6/GP130/JAK/STAT3 axis has been associated with cancer cachexia and neural invasion." (PMID 41397158, 2025). "Interleukin 6 (IL-6), enriched in cancer-associated adipocytes, and lipolysis-derived free fatty acids (FFAs) released from adipocytes, amplify ANGPTL4-mediated glycolysis and metastasis through activation of STAT3 and PPARα pathways in TNBC cells." (PMID 40616161, 2025). "A similar scenario exists in gastric cancer, where IL‐6 controls activities linked to angiogenesis, cancer inflammation and tissue remodeling, and IL‐11 instructs cancer cell survival and proliferation." (PMID 39673075, 2025). "Nonetheless, we were able to demonstrate in vitro that MDP-cMOPs differentiate into immunosuppressive macrophages in the presence of conditioned medium from 4T1p cancer cells, an effect associated with IL-6." (PMID 40822347, 2025). "Conversely, chronic inflammation associated with cancer cachexia leads to plasma IL6 elevation, which promotes muscle atrophy." (PMID 40448398, 2025). "Recently, in addition to IL-6, the involvement of nuclear factor-κB (NFκB) has been associated with cardiac atrophy induced by cancer cachexia." (PMID 39311910, 2025).
cancer (continued). "Consistent with previous findings, there was a notable positive association between IL-6 and cancer-associated fibroblasts (CAFs) (r=0.443, P<0.001)." (PMID 40433391, 2025). "Chronic inflammation is a major hallmark of cancer, IL-6 acts as an important pro-inflammatory cytokine." (PMID 40486873, 2025). "In GBM, the immune infiltration levels of regulatory T cells, neutrophil, macrophage, monocyte, dendritic cells, and cancer-associated fibroblasts are positively correlated with IL-6 expression." (PMID 39781345, 2025). "Slow-wave sleep (SWS) loss correlates with elevated IL-6 and shorter progression-free survival in cancer patients." (PMID 41357522, 2025). "Inflammation, regarded as a hallmark of cancer, contributed to tumorigenesis and cancer progression, closely linking IL-6 to the mechanisms underlying cancer development and advancement." (PMID 40160826, 2025). "Beyond its normal physiological roles, IL-6 has been strongly linked to cancer development and progression." (PMID 40149421, 2025). "Mouse models neutralising GDF‐15 or IL‐6 have confirmed the amelioration of muscle loss and therefore the potential for prolonged cancer survival." (PMID 41380167, 2025). "IL‐6 is a pro‐inflammatory cytokine implicated in muscle catabolism and cachexia, contributing to muscle wasting in patients with cancer." (PMID 41380167, 2025). "In cancer, high IL-6 levels stimulate hyperactivation of JAK/STAT3, often linked to poor BC patient outcomes." (PMID 40868199, 2025). "Moderators of the intervention type showed a significant association with IL-6 levels in the cancer subgroup (Q = 37.52, p < 0.001)." (PMID 40281902, 2025). "A longitudinal study of 71 cancer survivors suggested that attenuation in IL-1β, IL-6, TNF-α, and IL-10 was associated with either an increased sleep duration or decreased sleep problems." (PMID 41470834, 2025). "Targeting IL-6 holds promise for the management of cancer-associated inflammation and improvement of therapeutic outcomes." (PMID 40255422, 2025). "CRP, a pentraxin family protein released by hepatocytes in response to IL‐6, is a marker of increased cancer risk and worse prognosis." (PMID 40528380, 2025). "Cho and colleagues demonstrated that cancer-associated fibroblasts (CAFs) activated by cancer cells release IL-6 and GM-CSF cytokines, which synergistically induce monocytes to differentiate into M2 macrophages." (PMID 40495762, 2025). "Emerging biomarkers—galectin-3 and interleukin-6 (IL-6)—linked to cancer-related inflammation also appear to modulate atrial remodeling and arrhythmia susceptibility." (PMID 41155802, 2025). "The enhanced effect of cancer-associated fibroblasts (CAFs) on the capacity of lung tumor cells to metastasize is explained by the IL-6/STAT3 signaling system." (PMID 41179937, 2025). "Mutated TNF-α can directly contribute to cancer formation, while cytokines such as IL-6, IL-8, and IL-1β stimulate cell proliferation and cervical cancer progression." (PMID 40430101, 2025). "Interleukin-6 (IL-6) is a key cytokine in immune regulation, but its abnormal expression is linked to inflammation and cancer progression." (PMID 40557151, 2025). "The GSEA results suggested that several pathways associated with cancer progression were upregulated in patients with GBM who had high IL-6 mRNA expression." (PMID 39781345, 2025). "Our previous research demonstrated that Sinulariolide, a member of this group, effectively inhibits TGF-β-induced IL-6 secretion, thereby suppressing inflammation-associated cancer development." (PMID 41373438, 2025). "In cancer-associated inflammatory states, inflammatory cytokines such as IL-6 and TNF-α not only stimulate the synthesis of CRP but also inhibit the synthesis of albumin, accelerate its degradation, and promote vascular extravasation." (PMID 41415846, 2025).